IFNAR1 (interferon alpha and beta receptor subunit 1)
Diseases named in the same sentence as IFNAR1 in open-access papers (continued):
Sharing a sentence is not in itself a finding about the gene and the disease.
infection (continued). "Consistent with our screen and in contrast to the observations with separate cultures, we found that IFNAR1-disrupted cells in this context exhibited a significant competitive advantage over control cells during SARS-CoV-2 infection but not during mock infection." (PMID 37975674, 2023). "IFNAR1-Ab also increased single-round MDM infection by HIV-2 and HIV-1(O), but not HIV-1(M)." (PMID 36289397, 2022). "Overexpression of IRF7 in KO IFNAR1 cells infected with DTMUV partially restored the expression of IFN-β at 12–48 hpi, IFIT5 at 36–48 hpi, IRF1 at 48 hpi, and MX1 at 12–48 hpi, indicating a type I IFN-independent role of IRF7 in the induction of these genes during DTMUV infection." (PMID 35891486, 2022). "Thus, the IFNAR1 mediates SLE activity whenever chromatin release into the extracellular space boosts anti-chromatin immunity, e.g., cell death related to sunburns, trauma or NET release during infection." (PMID 36119023, 2022). "Therefore, we blocked in vivo type I IFN receptor (IFNAR-1) signaling at specific time points to investigate the relationship between type I IFN signaling and the pulmonary pathology induced by LCMV Arm infection." (PMID 35672321, 2022). "A key role for capsid in determining interferon induction in macrophages was identified by infection with HIV-1(M) chimeras bearing HIV-1(O) or HIV-2 capsid (CA), which could only replicate in MDM in the presence of IFNAR1-Ab, in common with wild type (WT) HIV-2/HIV-1(O)." (PMID 36289397, 2022). "Since PbA-infected Ifnar1-/- mice had markedly reduced numbers and frequencies of brain infiltrating effector cells – in particular CD8+ T cells – we assessed whether this was due to an impaired cytotoxic T cell response upon infection." (PMID 34659202, 2021). "However, Ifnar1-/- iMOs had reduced expression of Ly6C, and, after infection, did not upregulate surface expression of Major Histocompatibility Class II molecules (MHC-II) (top)." (PMID 34015056, 2021). "To explore whether SECoVs infection affects IFN receptors expression, we next compared the receptor expression of the three types of IFNs, including type I IFN receptors (IFNAR1 and IFNAR2), type II IFN receptors (IFNGR1 and IFNGR2), and type III IFN receptors (IL10RB and IFNLR1)." (PMID 35126380, 2021). "However, we observed higher frequencies of immature CD27+CD11b- NK cells in Ifnar1ΔNKp46 compared to Ifnar1fl/fl mice, suggesting a defect in the ability of NK cells to mature in response to ECTV infection in the absence of intrinsic IFNAR signaling." (PMID 34015056, 2021). "Infection of the progeny mice born to naïve KitW-sh/W-sh Ifnar1−/− Ifngr1+/+ mothers, with DENV2(D2Y98P) s.c., resulted in 30% mortality, compared to 90% mortality in KitW-sh/W-sh Ifnar1−/− Ifngr1−/− mice and lower clinical score, indicating the protective property of IFN-γ signaling." (PMID 34066286, 2021). "IFNAR1-deficient mice are highly susceptible to HSV, regardless of the route of inoculation, and rapidly succumb to infection, mainly due to a loss of viral control." (PMID 34047696, 2021). "At first glance the triplication of IFNAR1 and IFNAR2, with consequent upregulation of the anti-viral Type I interferon signaling, might suggest higher defenses in DS individuals in a first stage of the infection." (PMID 33479353, 2021). "Therefore, to assess the ability of CD8+ Tn cells to upregulate Ly6C during infection in the absence of IFN-I signaling we have infected Ifnar1−/− mice." (PMID 34489451, 2021). "Instead, Ifnar1-/- mice displayed statistically significant differences in viral load by day 5 in lung tissues, with all WT animals lacking detectable viral RNA by day 7 post-infection." (PMID 32330200, 2020). "However, no systematic measurement of IFN-I levels during infection were done in the studies using Ifnar1−/− mice or injections of anti-IFNAR antibodies." (PMID 33344264, 2020).
infection (continued). "Similarly, while we did detect increased and sustained HTNV RNA in the Ifnar1-/- mice, all but two animals were able to clear the infection by 14 days, demonstrating that type I IFN is not the only mediator of viral defense in non-reservoir rodents." (PMID 32330200, 2020). "While the mRNA delivery of hACE2 followed by infection with 5x104 FFU of SARS-CoV-2 did not allow our group to study viral pathogenesis in Ifnar1-/- mice, the delivery of hACE2 mRNA to our murine model allowed for the induction of a strong CD4+ and CD8+ T cell response to SARS-CoV-2." (PMID 33326500, 2020). "Interestingly, infection is also controlled in AMs lacking MAVS or IFNAR1, although virus and lysosome colocalization is less pronounced." (PMID 32545470, 2020). "IFNAR1-signalling also impaired germinal center B-cell formation, Ig-class switching, and Tfh cell differentiation thus impeding the resolution of non-lethal blood-stage infection of P. y." (PMID 33344264, 2020). "Importantly, on day 3, levels of these cytokines were lower in mock-infected Ifnar1-/- as well, suggesting an intrinsic defect in these animals irrespective of infection status." (PMID 32330200, 2020). "Collectively, the results of the experiments with LysMCre+Ifnar1fl/fl and Ifnar1−/− mice infected via the IVag route indicate that CD4+ T cells are required to mount an efficient Ab response, to control the local viral burden, and to reduce clinical signs and mortality following IVag infection." (PMID 30677097, 2019). "We added a blocking anti-Ifnar1 monoclonal antibody (mAb) to OVX, hormone treated, WT, and Ifnlr1−/− mice as ZIKV fails to antagonize type I IFN signaling in murine cells; indeed, in the absence of anti-Ifnar1 mAb treatment, little infection was observed at 7 dpi in WT or Ifnlr1−/− mice." (PMID 30655513, 2019). "However, genetic deletion of IFNAR1 or IFN-β did not alter the progressive course of infection seen in WT BALB/c mice." (PMID 29459858, 2018). "Unlike Ifnar1-/- mice, Caspase1-/- and Nlrp3-/- mice were not protected from IOE infection, thus we sought to further address a potential role for necroptotic cell death in driving HSPC loss during IOE infection." (PMID 30080899, 2018). "However, in contrast to WT mice, Ifnar1-/- mice failed to control bacterial growth at later time points resulting in significantly higher bacterial burdens in lungs at 24 and 48 h post infection (p.i.)." (PMID 29112952, 2017). "Compared to Ifnar1−/− mice, Tim1−/− Ifnar1−/− mice demonstrated less fecal HAV shedding, as well as a 0.5-log-unit difference in the abundance of viral RNA in the liver, smaller increases in ALT levels, and lower cytokine levels 14 days after infection with gradient-purified eHAV or HAV." (PMID 28874468, 2017). "Indeed, Mx1 was not upregulated in RRV-infected NOD.IFNAR1−/− mice, indicating that their lymphocyte activation from day 5 post infection occurred independently of type 1 interferon secretion." (PMID 27405244, 2016). "Similarly, the cecal expression of Mx1 was largely upregulated after PR8 infection in the WT mice, but not in the Ifnar1-/- mice, and as anticipated the level of induction of Mx1 tended to be lower overall in the Ifnar1-/- mice compared to WT mice." (PMID 27149619, 2016). "Interestingly, on day 4 post-infection the vast majority of infected cells in Ifnar1-/- mice were located in the lamina propria region and not the epithelium as on day 1, whereas virus antigen remained associated with IECs in Ifnlr1-/- mice." (PMID 25849543, 2015). "Notably, during infections with Listeria monocytogenes, IFNAR1 does not contribute to the early monocyte emigration from the BM within the first 24 hours." (PMID 22911155, 2012). "Interestingly, Ifnar1−/− mice displayed significantly lower numbers of inflammatory monocytes and neutrophils during early infection stages and lacked the late massive neutrophil influx." (PMID 22911155, 2012).
infection (continued). "Similarly, neuronally-produced Ifna1 may be required for microglial and MC interferon-signaling and anti-viral responses in WNE – potentially more so in MCs, since MCs and not microglia expressed its cognate receptor, Ifnar1 during infection." (PMID 37016414, 2023). "To corroborate whether MCs were able to degranulate in response to SFTSV in vivo, we examined serum levels of the MC-specific proteases tryptase and chymase in both WT mice (nonlethal SFTSV-infection model) and anti-IFNAR1 IgG-treated mice (lethal SFTSV-infection model)." (PMID 35612327, 2022). "However, currently, the most widely used animal model of SFTSV infection is mice deficient in type I IFN signaling (e.g., Ifnar1-/-), because adult immunocompetent mice infected with SFTSV have a very low viral replication rate and show few to no signs of infection." (PMID 35746656, 2022). "To test whether favipiravir had efficacy against BRBV-STL in vivo, we inoculated Ifnar1-/- mice via IP route with 4 x 102 pfu of BRBV-STL and treated the mice twice daily with 150 mg/kg of favipiravir in 0.5% methylcellulose via oral gavage for 8 days beginning immediately after infection." (PMID 31194854, 2019). "Moreover, the thriving of Proteobacteria after PR8 infection in the WT but not Ifnar1-/- mice supports our hypothesis that influenza virus is able to alter the intestinal microbiota, and that this action is dependent on IFN-Is." (PMID 27149619, 2016). "However, CD4+ T cell activation was absent from NOD.IFNAR1−/− mice until day 14 post infection." (PMID 27405244, 2016). "However, at day 1 post infection where the bacterial load was not affected in the infected Ifnar1-/- the converse was true with an increase in both type I and type II IFN-inducible genes suggesting a direct role of type I IFN signaling in suppression of this response." (PMID 26918359, 2016). "The exact mechanism for the differential induction of type-1 IFNs through IFNAR1 signaling in OE cells is not known, though we hypothesize that it likely depends on the cytokine composition of the supernatants at that particular time during infection." (PMID 25798928, 2015). "However, Julien and coworkers have observed that up-regulation of SOCS-1 and SOCS-3 in IAV-infected cells is IFNAR1-dependent, which does not contradict with our observation, because we found that the culture supernatants at the later stages of infection indeed stimulated SOCS-1 expression." (PMID 24391501, 2014). "Furthermore, because cells infected with 54DM virus show a similar level of IFNAR1 reduction as with WT or 54R infection, this indicates that ORF54 dUTPase enzymatic function is not required for the degradation of IFNAR1 and the inhibition of the type I IFN signaling cascade." (PMID 21998588, 2011). "Furthermore, in either WT-5 or KR-2 cells, infection with HSV hardly induced any STAT1 phosphorylation indicating that an increase in IFNAR1 degron phosphorylation may not rely on HSV-induced production of Type I IFN." (PMID 21695243, 2011). "At 5 days post-infection, mice lacking the IFN-I interferon receptor (IFNAR1) exhibited markedly elevated spirochetal burdens at the site of inoculation, indicating that IFN-I is required to restrict early bacterial expansion." (PMID 41727126, 2026). "At the later time point, when Tollip levels were reduced, levels of IFNAR1 and IFNGR1 increased relative to the non-targeting control but remained lower than at the time of infection." (PMID 40558091, 2025). "Protein lysates collected after interferon pre-treatment, but prior to infection, showed decreased levels of representative ISGs IFIT1 and MX1 upon CPSF6 knock-out, though not to the same extent as observed upon IFNAR1 knock-out." (PMID 41385587, 2025). "Depletion of CD8+ T cells, but not neutrophils, rescued mice from lethal disease, demonstrating that IFNAR1 is required to prevent T cell exhaustion and virus persistence in LCMV-Arm infection, and in the absence of IFNAR1, PD-L1 is required for survival." (PMID 38543756, 2024).
infection (continued). "Protein lysates collected after interferon pre-treatment, but prior to infection, showed decreased levels of a representative ISG, MX1, upon CPSF6 knock-out, though not to the same extent as observed upon IFNAR1 knock-out." (PMID 39678349, 2024). "Consistent with the results of infection activity, ISG expression was induced by IFNβ treatment in PK-15 Ifnar1 k/o cells reconstituted with IFNAR1 (WT) but not in other cells." (PMID 37939052, 2023). "While we did not observe differences in IFNAR1, IRF3, STAT1, nor ISG15 expression induced by the two strains, IFNβ, LPG2, RIG1, and OAS1 were significantly induced after infection with Mb3601, but not H37Rv." (PMID 34307535, 2021). "In line with our in vitro results and the HCV data, infection of Ifnar1Δ/Δ and Ifnar1+/+ control mice with LCMV Cl13 led to induction of Tdo2 expression in wild type, but not in conditional IFNAR1 knock out mice." (PMID 33045014, 2020). "Viremias in IFNAR1−/− dams were similar after infection with ZIKV-MY or ZIKV-Natal, and importantly, infection of fetal brains was also not significantly different." (PMID 30282919, 2018). "The absence of IFNAR1 results in increased bacterial loads during both subcutaneous GBS infection of neonate mice and intravenous infection of adult animals." (PMID 28082986, 2016). "Similar to our findings regarding the colonic burden, prior infection with PR8 enhanced the ability of S. Typhimurium to disseminate to the MLN and the lungs in WT but not Ifnar1-/- mice." (PMID 27149619, 2016). "However at day 3 post infection diminished expression of Stat1 was observed across all three tissues, following infection in the Ifnar1-/- compared to the WT mice, which may be explained by a dependence on type I IFN signaling or may result from the lower bacterial load in the Ifnar1-/-." (PMID 26918359, 2016). "MHC I expression was upregulated on pDCs in MLN and PLN on day 3 post infection in NOD, but not NOD.IFNAR1−/− mice." (PMID 27405244, 2016). "Under the conditions used in our experiments in KR-2 cells to influence the phosphorylation of IFNAR1 degron, an induction of PERK phosphorylation (indicative of its activation) was observed in response to thapsigargin but not to infection with HSV." (PMID 21695243, 2011). "At day 2 post-infection with rMA15 virus, lung lesions in STAT1−/− mice were indistinguishable from those seen in 129 WT, IFNAR1−/− and IFNGR−/− infected animals." (PMID 20386712, 2010). "Although interferon alpha and beta receptor subunit 1 (IFNAR1) knockout (KO) mice have been widely used to study JEV infection, they only display peripheral pathological responses and do not exhibit neurological symptoms after infection with JEV." (PMID 40855992, 2025). "Similarly, virus-specific CD8+ T cells in IFNAR1 KO mice treated with and without anti-PD-L1 monoclonal antibody in the subacute (from day 15) or chronic (from day 24) phase of LCMV-Arm infection, also demonstrated a reduced expression of effector cytokines." (PMID 38543756, 2024). "Mice genetically deficient in type I IFN receptor (Ifnar1−/−) succumb rapidly to infection by RRV or other alphaviruses within 4 days, and for CHIKV, bone marrow chimera experiments showed that IFNAR1 expression is required on nonhematopoietic cells for infection control and survival." (PMID 39535221, 2024). "However, Ifnar1 and Ifnar2 were lowly expressed in IFN-act TN (T8) cells; therefore, we indicated that IFN-act TN cells possibly secrete type I IFN after infection with E. granulosus and produce a nonpreferential immune response." (PMID 37039643, 2023). "Therefore, we measured the levels of intracellular GABA, the intermediate product of glutaminolysis, and found that Ifnar1-/- but not Irf9-/- had higher levels of GABA before and after infection." (PMID 34237114, 2021).
infection (continued). "We also found that deletion of signaling molecules that act upstream of type I IFN production including multiple TLRs, RIPK2, cGAS/STING, or MAVS pathways, did not increase BMDM fusion during infection while control BMDMs lacking MyD88 and TRIF or IFNAR1 extensively fused." (PMID 32150572, 2020). "Whilst loss of IFNAR1 or IFNAR1 blockade initially increases LCMV-Cl13 titres, suggesting that IFNAR blockade cancels the antiviral effects of IFN-I effectively, by day 30 post infection virus levels are reduced compared with mice that did not receive blockade." (PMID 30791575, 2019). "Infection of mice by persistent MNoV strain CR6 was found to be enhanced by the presence of intestinal commensal bacteria, a dependence that was abrogated in mice lacking Ifnlr1, but not Ifnar1." (PMID 29361691, 2018). "To assess whether IOE infection induced apoptosis we evaluated Annexin V staining, and found increased Annexin V+ HSPCs in response to IOE infection in WT, but not Ifnar1-/- mice." (PMID 30080899, 2018). "Given the low level of infection by ZIKV in both WT and Ifnar1 KO PNS cultures, it was not possible to ascertain whether type I interferons play a role there too." (PMID 28645311, 2017). "However, unlike in the A129 model, after infection with 100 focus-forming units (FFU) of ZIKVAS via the subcutaneous route, all Ifnar1-/- animals perished within 10 days." (PMID 28672028, 2017). "However, uninfected WT and Ifnar1-/- mice were found similarly colonized with SFB; furthermore, the SFB abundance did not significantly change in the Ifnar1-/- mice, despite PR8 infection." (PMID 27149619, 2016). "Moreover, depletion of IFNLR1, but not IFNAR1, resulted in a 3-fold increase in the HEV RNA abundance and infectious virus production, suggesting that HEV replication is restricted by the type III IFNs induced by infection." (PMID 28558073, 2017). "However, in WT but not Ifnar1-/- mice, PR8 infection enhanced cecal Muc2 levels." (PMID 27149619, 2016). "Indeed, as expected, S. Typhimurium numbers in the colon content were low and highly variable in S. Typhimurium-only infected WT and Ifnar1-/- mice, whereas prior infection with PR8 was still able to increase S. Typhimurium gut colonization in WT, but not in Ifnar1-/- mice." (PMID 27149619, 2016).